CRP (C-reactive protein)
Diseases named in the same sentence as CRP in open-access papers (continued):
Sharing a sentence is not in itself a finding about the gene and the disease.
tumor (continued). "IL-6 also helps in binding CRP to phospholipids on tumor cells that results in activation of classic C1q complement pathway." (PMID 26693355, 2015). "On POD 3, Hb, CRP, albumin administration on the postoperative day, lymph node involvement, SCr, and tumor site were effective variables." (PMID 26530188, 2015). "In our previous report, CRP level was an important factor for survival, and correlated with unfavorable tumor characteristics of HCC." (PMID 26498833, 2015). "Clinicopathological factors, including age, gender, tumor size, histological subtype, tumor grade, microvascular invasion, histological tumor necrosis, C-reactive protein levels and performance status were reviewed." (PMID 25435945, 2015). "Elevated CRP, tumor stage, resection margin status, and lymph node density (P = 0.02) were independent predictors of CSS." (PMID 26496339, 2015). "C-reactive protein (CRP) an acute-phase reactant inflammatory protein is synthesized in hepatocytes in response to cytokines that are released from leucocytes within the tumor microenvironment." (PMID 26693355, 2015). "CRP serum levels, tumor stage, patients’ age, tumor size and histological grading were analysed as prognostic parameters for OS by calculating univariate and multivariable survival analysis." (PMID 26248232, 2015). "In fact, as expected, patients with negative cytology and positive CP demonstrated the lowest PE tumor marker values and the highest CRP levels." (PMID 26691279, 2015). "We previously demonstrated that C-reactive protein (CRP) elevation in OSCC is associated with poor survival and tumor invasiveness." (PMID 26292957, 2015). "Host immune system responds to tumor growth with elevated inflammatory cytokines (such as interleukin-6) and subsequently elevates the serum CRP levels." (PMID 26292957, 2015). "Somewhat differently, serum CRP levels showed a linear correlation of the incidence of LR, after adjusting for age, maximal tumor dimension and tumor numbers." (PMID 25602444, 2015). "When we combined these two markers, a strong correlation was found between both higher CYPFRA 21-1 and CRP levels and tumor stage, nodal metastasis, skin invasion, and bone invasion." (PMID 26292957, 2015). "CRP itself seems to induce further inflammatory response and possibly leading to a self-sustaining circle of tumor progression and inflammatory response." (PMID 26248232, 2015). "In clinical practice, it is suggested that elevated serum CRP levels combined with tumor characteristics can predict different types of HCC recurrence more effectively, though the exact underlying mechanism remains to be further investigated." (PMID 25602444, 2015). "CRP and Alb are acute phase proteins and their concentrations are related to the presence of an inflammation or neoplasm." (PMID 26339617, 2015). "In this study, some conventional and economical markers such as LDH, CRP, Na+, Cl- and other two tumor biomarkers(CEA, NSE) were selected based on previous studies to establish the GEP model for the detection of SCLC." (PMID 25996920, 2015). "Inflammation is a critical part of tumor progression and CRP seems to act not only as a biomarker for the process of inflammation and/or tumor progression but also represents a modulator of the immunological system." (PMID 26248232, 2015). "As reported, CRP can promote tumor progression through a variety of possible ways, including anti-apoptotic activity and tumorigenic potency, T-cell function damage, increased levels of serum angiogenic factors, and resistance to chemotherapy." (PMID 25602444, 2015). "The results suggest that tumor-size reduction depends on initial tumor size and the organs involved, as well as systemic reaction to the lung tumor, as indicated by CRP levels." (PMID 24612599, 2014). "Spearman's rank correlation between pre-operative CRP level in peripheral blood and metagene expression in the tumor tissue." (PMID 25340395, 2014).
tumor (continued). "The circulating CRP acts on tumor cells, which lead to tumor cell lysis and facilitate tumor progression." (PMID 24800842, 2014). "For lesions < 20 mm, patients with low CRP had significantly greater reductions in tumor diameter than patients with high CRP (−43.8 ± 33.4% vs. −15.3 ± 37.7%, P = 0.0019)." (PMID 24612599, 2014). "Administration of CRP to H22 tumor-bearing mice at a dose of 100 mg/kg per day decreased tumor sizes by 59.5%−83.8% and 53.9% within 48 h and 14 days, respectively." (PMID 25257786, 2014). "The present study demonstrates that concurrent high levels of both SCC-Ag and CRP at the diagnosis of recurrence acts as a predictor of recurrent tumor status, recurrent advanced tumor stage, distant metastasis, and survival after the diagnosis of recurrence." (PMID 25061977, 2014). "This study aimed to assess the association between initial tumor size, involved organs, pre-treatment C-reactive protein (CRP) levels, and reduction in tumor size in patients with clear cell RCC (CCRCC) treated with sunitinib." (PMID 24612599, 2014). "The supportive role of the tumor micro-environment is represented by proteins involved in avoiding immune destruction and inducing tumor-promoting inflammation (CRP, C9, SERPINA3)." (PMID 25114662, 2014). "We have recently identified recurrent mutations at the SNP position -286 (rs3091244) in the promoter of CRP gene in several tumor types, instead suggesting that locally produced CRP is a potential driver of tumorigenesis." (PMID 25025473, 2014). "Serum level of IL-8 increased proportionally along with TNM tumor stage and was found to be statistically significant correlated with C-reactive protein (P -value, R=0.64)." (PMID 25408728, 2014). "We then wanted to elucidate potential relations between pre-operative CRP level measured in peripheral blood, as a marker of systemic inflammation, and ongoing processes in the local tumor tissue environment." (PMID 25340395, 2014). "Both, tumor and host cells produce different mediators, for example, C-reactive protein (CRP), proinflammatory cytokines with tumor necrosis factor-α (TNF-α), interleukin-6 (IL-6), interferon-γ (IFN-γ), and adipocytokines." (PMID 25049439, 2014). "Extrahepatic production of CRP has also been found in tumor cells, monocytes, lymphocytes and neuron as a part of local inflammation, but the amount is too little to affect serum CRP." (PMID 24800842, 2014). "The reasons why CRP levels correlated with prognosis in tumor patients including OS remain to be determined." (PMID 24800842, 2014). "The second theory has also been supported by several authors who recently demonstrated that tumor cells can express IL-6 and even CRP." (PMID 23642165, 2013). "The CRP-level correlated significantly with the tumour stage: 36.4 and 78.9% of all patients with a CRP ≤ and >5 mg/l suffered from muscle invasive disease (pT≥2) at the time diagnosis (p<0.001, Fisher’s exact test)." (PMID 23497335, 2013). "IL-6 is not only upregulated in tumor cells but—together with its target, C-reactive protein (CRP)—present at elevated levels in the sera of WM patients." (PMID 24106612, 2013). "Of these, elevated ALT, Child-Pugh class, tumor size, tumor multiplicity, presence of PVT, presence of metastasis, elevated AFP, high CRP and high NLR were significantly associated with poorer survival." (PMID 23409924, 2013). "In subjects with detailed data of inflammation and tumor markers, we analyzed the correlation between changes in CRP levels and changes in tumor markers after IVC therapy." (PMID 23947403, 2013). "The levels of CRP have been inversely related to tumor-infiltrating CD4+ T-lymphocytes within the tumor microenvironment, which in turn carriers a poor prognosis." (PMID 23409924, 2013). "The liberation of multiple proinflammatory cytokines, including IL-1, IL-6, and TNF-α from the tumor microenvironment results in the induction of CRP synthesis from the liver." (PMID 24130817, 2013).
tumor (continued). "Second, CRP affects tumor growth and survival by enhancing tumor cell proliferation and protecting tumor cells from drug-induced apoptosis." (PMID 23724031, 2013). "High inflammation or tumor burdens, as measured by CRP or tumor antigen levels, tend to lower peak plasma ascorbate levels after IVC." (PMID 23947403, 2013). "• Patients with higher inflammation or tumor burdens, as measured by CRP levels or tumor antigen levels, tend to show lower peak plasma ascorbate levels after IVC." (PMID 23947403, 2013). "C-reactive protein (CRP) was a significant independent predictor of tumor recurrence in HCC with malignant portal vein invasion after surgery." (PMID 23618082, 2013). "The elevation of CRP arises from the host immune responses to tumor growth with elevated inflammatory cytokines." (PMID 23383155, 2013). "The elevation of both SCC-Ag and CRP levels was correlated with the standardized uptake value (SUV) max of the tumor (≥8.6 mg/L) and lymph nodes (≥5.7 ng/ml) (P = 0.019)." (PMID 23383155, 2013). "There was a significant correlation between CRP concentrations and Child-Pugh class or tumor stage (r = 0.311, p < 0.001; r = 0.475, p < 0.001, respectively)." (PMID 23409924, 2013). "The present study demonstrated that the presence of high levels of both pre-treatment SCC-Ag and CRP acts as a predictor of clinical stage, clinical tumor status, and clinical nodal status in patients with PLC." (PMID 23383155, 2013). "Regarding the clinicopathological factors influencing patient survival, only tumor status (P = 0.020) and CRP (P = 0.010) had significant influences on overall survival (OS) in the univariate analysis." (PMID 23383155, 2013). "Consistent with survival analysis, there were significant differences in tumor response on the combined use of serum CRP level and NLR." (PMID 23409924, 2013). "In those cases, there was a strong correlation (R 2 = 0.6) between the change in tumor marker and the change in CRP during IVC therapy." (PMID 23947403, 2013). "Several studies have reported that CRP is a useful serum marker for patients with RCC, and elevated serum CRP levels have been shown to be associated with tumor aggressiveness, recurrence, and poor prognosis." (PMID 22857740, 2012). "A proinflammatory state is recognized by elevated infiltrating macrophages, T cells, tumor necrosis factor-alpha and C-reactive protein in the tumor microenvironment, and it is commonly present in patients with MetS." (PMID 22911869, 2012). "In patients for whom both tumor marker and CRP data are available, we found an interesting correlation: patients who had reduced CRP levels tended to also have reduced tumor marker values." (PMID 22963460, 2012). "Apart from the degenerative changes, the findings of CRP-positive foci outside the tumor and within liver tissue with preserved lobular architecture are most intriguing." (PMID 23024866, 2012). "These smaller trials have shown a potential relationship between circulating CRP levels and tumour stage as well as a significant impact on the prognosis of patients with RCC." (PMID 22958305, 2012). "The CRP-level correlated significantly with the tumour stage: 19.3, 30.2, and 63.2% of all patients with a CRP ≤4, 4–10, and >10 mg/l suffered from locally advanced (pT ≥ 3, Nany, Many) RCC at the time diagnosis (p < 0.001, Chi2 test)." (PMID 22958305, 2012). "The 2 different mutational backgrounds of IHCA concerning gp130 and STAT3 lead to a similar morphology and immunophenotype of increased SAA/CRP in the tumor hepatocytes." (PMID 23024866, 2012). "The presence of vascular abnormalities beyond the tumor and beyond the CRP foci needs further study, especially due to the similarities with the changes in the HCA." (PMID 23024866, 2012).
tumor (continued). "Concentrations of serum VEGF were in a positive correlation with tumour size (p = 0.003), plasma C-reactive protein (CRP) concentrations (p = 0.007), white blood count (WBC) in peripheral blood sample (p < 0.001) and metastatic stage of disease (p = 0.041)." (PMID 23412843, 2012). "The liberation of multiple proinflammatory cytokines, including interleukin-1 (IL-1), IL-6, and tumor necrosis factor-α from the tumor environment eventually results in the induction of CRP synthesis from the liver and other tissues." (PMID 22103888, 2011). "The multifactor-adjusted HR of reduced overall survival for the highest versus the lowest tertile of CRP was 8.63 (2.04 to 36.4) among women with HER2 positive tumours." (PMID 21639875, 2011). "The CRP level in tumor diameter > 3 cm was significantly higher than that in tumor diameter < 3 cm (P < 0.001)." (PMID 21569644, 2011). "The pre-operational CRP level of stage I NSCLC is positively related to the maximum diameter of tumor." (PMID 21569644, 2011). "Multiple linear regression analysis suggested the maximum diameter of tumor was closely related to the level of serum CRP." (PMID 21569644, 2011). "A trend towards an increase in cytoplasmic and nuclear CRP presence from hormone sensitive to hormone refractory tumours was noticed." (PMID 22110984, 2011). "Tumour tissue concentrations of IL-1β protein correlated with serum CRP concentrations (r = 0.31, P = .05; linear regression) and tumours with diffuse or patchy inflammatory cellular infiltrate were associated with elevated serum CRP." (PMID 21760776, 2011). "Serum Ang-2 and VEGF-A levels increased with tumour T stage (P=0.007 and P=0.025, respectively) and N stage (P=0.02 and P=0.03, respectively), and correlated with CRP levels (r=0.43, P<0.001 and r=0.23, P<0.001, respectively)." (PMID 21081932, 2011). "Among women with HER2-positive tumours, the multifactor-adjusted HR of reduced overall survival for the highest versus the lowest tertile of CRP was 8.63 (2.04 to 36.4)." (PMID 21639875, 2011). "Interleukin-6, produced by the tumor or surrounding cells, stimulates liver production of acute-phase reaction proteins (such as C-reactive protein (CRP) and fibrinogen) in both the fasted and fed states." (PMID 21176210, 2010). "Here, it was the first time ever to study the correlations between tumor size, leukocytic count and serum CRP level in the EAC-solid-tumor model." (PMID 19341447, 2009). "The significance of serum elevation of CRP as an indicator of tumour malignant potential and outcome of patients has been investigated in human gastrointestinal carcinomas, renal cell carcinoma, ovarian carcinoma and myeloma." (PMID 27956962, 2009). "After the tumor resection, fever disappeared and CRP dropped gradually from 16.7 to 2.7, but the patient had recurrence with multiple liver metastasis and pleuritis carcinomatosa and died on February 2, 2006, 79 days after the operation." (PMID 19707535, 2009). "DHA (125, 250 mg/kg) elicited significant, dose-dependent reductions in tumor size (38%, 79%; respectively), as well as in LC, CRP and MDA levels." (PMID 19341447, 2009). "An explanation would be that cellular CRP indicates the immediate inflammatory response to tumour invasion, while its serum expression indicates the later systemic reaction." (PMID 27956962, 2009). "The acute phase synthesis of CRP is upregulated by proinflammatory cytokines as interleukin-1, interleukin-6, and tumour necrosis factor, which act as autocrine growth factors for neoplasm." (PMID 27956962, 2009). "In this paper, we described the relationship between CRP levels and tumor invasion depth, LN metastasis, and TNM stage." (PMID 19457231, 2009). "In this study, the serum levels of both IL-6 and CRP evidenced statistically significant differences in tumor size, tumor invasion depth, and LN metastasis." (PMID 19457231, 2009). "We found that leukocytic count and CRP level were significantly increased in response to a mount in tumor size." (PMID 19341447, 2009).
tumor (continued). "HCC produce proinflammatory cytokines such as IL-8 by autocrine or paracrine, which lead to CRP production and inflammatory cascade or tumor progression." (PMID 19707535, 2009). "This is consistent with other studies that found a positive correlation between elevated CRP concentrations, before surgery and a poor outcome in patients who had curative primary tumour resection." (PMID 17211465, 2007). "There is an inverse relationship between CRP levels and tumour lymphocyte infiltration, with a raised CRP concentration indicative of a weak infiltration of lymphocytes at the periphery of the tumour." (PMID 17211465, 2007). "The tumour COX-2 expression was directly associated with the tumour CD4+ (P<0.01) and CD8+ (P<0.05) T-lymphocytic infiltrate and weakly with C-reactive protein (P=0.068)." (PMID 17024120, 2006). "Firstly, that an elevated C-reactive protein identifies tumours capable of producing significant amounts of proinflammatory cytokines, in particular interleukin-6 and therefore with the potential for more rapid growth of tumour cells." (PMID 16523196, 2006). "Tumour volume was correlated with C-reactive protein (r2=0.20, P=0.002), interleukin-6 (r2=0.20, P=0.002) and interleukin-10 (r2=0.24, P=0.001)." (PMID 17003778, 2006). "One possible explanation is that C-reactive protein can be measured with greater accuracy and precision than tumour-based factors." (PMID 17024120, 2006). "In the present study, median IL-1β concentrations were 10–100-fold higher than IL-6 in the tumour tissue and there was a weak but significant correlation between tumour tissue IL-1β concentration and serum CRP." (PMID 17088911, 2006). "Tumour volume was weakly correlated with C-reactive protein (r2=0.20, P=0.002), interleukin-6 (r2=0.20, P=0.002) and interleukin-10 (r2=0.24, P=0.001)." (PMID 17003778, 2006). "There were a greater number of males (P<0.05) and tumours were larger (P<0.05), had more vascular invasion (P<0.05) and had poorer differentiation (P<0.05) in the elevated C-reactive protein group." (PMID 15597096, 2005). "The number of tumor samples with values greater than the largest value for normal samples was 17/30 for CRP (p = 3.1 × 10-7) and 13/30 for SAA (p = 2.3 × 10-5)." (PMID 16117833, 2005). "One possible explanation is that C-reactive protein can be measured with greater accuracy and precision than tumour T-lymphocytic infiltration." (PMID 15700032, 2005). "On univariate survival analysis, stage (P<0.05), tumour type (P<0.01), performance status (P<0.001), white cell count (P<0.01), albumin (P<0.001) and C-reactive protein (P<0.01) were significant predictors of survival." (PMID 12966420, 2003). "UBCS039-pretreated tumor-bearing mice also presented increased CRP levels in their blood." (PMID 41530841, 2026). "Multivariate analysis confirmed that tumor history, CRP, ferritin level, sCD25, lactate, SOFA score and time to treatment initiation, chemotherapy, glucocorticoid monotherapy, gamma globulin treatment were independent prognostic factors affecting OS in HLH patients." (PMID 42063782, 2026). "Multivariate analysis was further employed, and the results showed that tumor number (HR, 2.221; 95% CI, 1.382-3.571; p = 0.001), extrahepatic metastasis (HR, 1.797; 95% CI, 1.081-2.987; p = 0.024), and CRP (HR, 1.775; 95% CI, 1.065-2.957; p = 0.028) were independently associated with OS." (PMID 40677718, 2025). "Integrating hemorheological data with established biomarkers—such as the neutrophil-to-lymphocyte ratio, CRP levels, or circulating tumor DNA—will further facilitate the distinction between immunotherapy-related alterations and systemic responses, creating a more reliable predictive framework." (PMID 40563651, 2025). "However, recent studies showed that the combination of TK1 with inflammatory biomarkers such as canine C-reactive protein (cCRP) can enhance the sensitivity for early tumor detection." (PMID 40351765, 2025).